TNF (tumor necrosis factor)
Diseases named in the same sentence as TNF in open-access papers (continued):
Sharing a sentence is not in itself a finding about the gene and the disease.
tumor (continued). "IL-1β and TNF-α, in particular, show a notable overlap of biological activity in cancer and promote tumor angiogenesis by inducing tumor cells to secrete VEGF via the IκB/TSC1/mTOR pathway." (PMID 33925400, 2021). "Th1 cells produce interferon gamma (IFN-γ) and tumor necrosis factor alpha (TNF-α), which promote cellular immunity to initiate effective anti-tumor response." (PMID 33639614, 2021). "TNF-α is a classical pro-inflammatory cytokine produced by activated monocytes, macrophages, CAFs, adipocytes, and tumor cells, among others." (PMID 34064859, 2021). "Anti-CTLA-4 monoclonal antibodies have also been shown to induce the release of TNFα against tumour cells via CD16 binding to antibody-bound tumour cells, and simultaneously to induce Treg inactivation." (PMID 33995362, 2021). "Th1 cells are characterized by the production and release of IFN-γ, which support tumour cytotoxicity synergistically with TNF-α." (PMID 34073106, 2021). "Single cells and/or clusters of cells were quantified within control and TNFα-activated skin window chamber B16F10 κB5-FLuc tumor-bearing animals over time." (PMID 33652682, 2021). "Together, the different observations propose that the persistent presence of TNFα and IL-1β at the tumor site contributes to chronic inflammation in BC and that the two cytokines play key roles in advancing disease course." (PMID 33806906, 2021). "Fold initial signal (normalized to basal signal) demonstrated variability between individual tumor cells as well as between control and TNFα-treated animals." (PMID 33652682, 2021). "Subsequently, chemokines promote CTL migration from peripheral immune organs into the tumor site and killing of tumor cells through the perforin-granzyme, Fas-FasL, and TNF-TNFR pathways." (PMID 34233576, 2021). "Inducing a cascade of signaling molecules, i.e., pro-tumorigenic cytokines interleukin-6 (IL-6), IL-8 and tumor necrosis factor-α (TNF-α), induces the NF-κB transcriptional survival program, protecting tumor cells against cell death." (PMID 34439134, 2021). "To further examine the role of TNFα in cGAMP-induced anti-tumour effects, we utilized anti-TNFα neutralizing antibody (Ab)." (PMID 34285232, 2021). "Intratumoural TNFα injection induced 10% tumour EC apoptosis, and co-treatment with TNFα and IFNγ further increased tumour EC apoptosis to 22%." (PMID 34285232, 2021). "In contrast, significant elevation in TNF-α level was observed in the serum as well as in the DMBA-induced tumor tissues of rats after the supplementation of a low dosage of theacrine." (PMID 34946538, 2021). "Mechanistically, TRAF2 loss was shown to enhance CPI efficacy by lowering the tumor necrosis factor (TNF) cytotoxicity threshold and increasing T cell-mediated tumor cell apoptosis." (PMID 33508232, 2021). "TNF is a major regulator of inflammation that is overexpressed and mainly secreted by macrophages in the tumor microenvironment." (PMID 34873410, 2021). "Based on the KEGG analysis, we found that these DEGs were involved in inflammation-related (cytokine-cytokine receptor interaction, chemokine signaling pathway, and NF-κB signaling pathway) and tumor-related (TNF signaling pathway) pathways." (PMID 34917146, 2021). "Proinflammatory factors related to the tumor microenvironment include IL-6, IL-8, TNF-α, TNF-β, and FASL; the main relevant cytokines are IL-1, IL-2, IL-12, and IFN-γ." (PMID 34194957, 2021). "These cells are able to kill tumor cells using soluble molecules of the tumor necrosis factor (TNF) family." (PMID 34305910, 2021). "In the following sections, we will interpret a possible role of targeting TNF-α interactions with the herbal extract platform in the tumor." (PMID 34916928, 2021). "Appropriately, colon biopsies from TAK-242 and Abx treated mice secreted considerably lower amounts of tumor-promoting cytokines, such as IL-1β and TNF-α." (PMID 34025672, 2021).
tumor (continued). "Although tumor inoculation of the 4T1 cell line generated greater levels of TNF-α, IL-1β, IL-6 in the spleen, serum, primary tumor, and liver, the IL-1β cytokine increased only in the cortex and hippocampus." (PMID 34572719, 2021). "By examining the functional properties of T cells in the tumor-draining LNs in mice that had received treatments for 5 weeks, we detected higher numbers of IFNγ and TNFα-producing CD4+ and CD8+ T cells after in vitro restimulation." (PMID 33408092, 2021). "This anti-tumor effect appeared to be mediated by the induction of pro-inflammatory cytokines like IL-6, TNF-α, and IFN-γ." (PMID 34177955, 2021). "The combination of biotherapy and PTT achieves highly effective tumor suppression and enhances the therapeutic effect by promoting the production of TNF‐α and IL‐4 to trigger cellular immunity and humoral immune response." (PMID 33854892, 2021). "miR-155 was previously shown to regulate inflammatory cytokine production (IL-6, IL-10 and TNFα) in tumor-activated macrophages via targeting CEBPB." (PMID 33540559, 2021). "We also found that cytokines, including interferon-gamma (IFNγ) and tumor necrosis factor-alpha (TNFα) secreted by activated T cells, damaged tumor cells in a cell contact-independent manner." (PMID 32666260, 2021). "As we have previously shown, the BATTLE trial data shows TNF and other target genes are tumor promoting in EGFR mutant patients treated with EGFR TKIs, and we confirmed tumor's TNF was elevated by EGFR TKI therapy in vitro, in vivo, and in patients." (PMID 33373873, 2021). "TNF signaling was a well-established tumor-promoting pathway by either helping tumor cells resist apoptosis or inducing an immune suppressive tumor microenvironment in HNSCC." (PMID 34691075, 2021). "Combined with age, gender, tumor grade, and stage of BLCA, TNF-based risk score still remained an independent risk factor (p < 0.001) in multivariate Cox analysis." (PMID 35174161, 2021). "The experiment determined the secretion levels of tumor TNF-α, IL-6, and IL-10 in RAW264.7 cells after treatment with different MP concentrations." (PMID 34436307, 2021). "Apart from suppressing T-cell proliferation and activation, experiments have shown that CD276 downregulates several cytokines, such as IFN-γ, TNF-a, and IL-2, while in vitro studies suggest its potential role in tumor invasion and metastasis as well." (PMID 33918733, 2021). "Among these cytokines, tumor necrosis factor- alpha (TNF-α) is a key inflammatory cytokine and involves in the inflammatory response during tumor development." (PMID 33730072, 2021). "As a result, the final tumor weight was dramatically reduced in the TNF-α-stimulated mice compared to that in the unstimulated mice." (PMID 34158609, 2021). "In vitro, C1q displays an anti-tumor effect in SKOV3 cells by promoting apoptosis through the upregulation of the TNF-α pathway and the downregulation of the mammalian target of rapamycin (mTOR) survival pathway." (PMID 34359708, 2021). "In the TIME, anti-tumour M1 macrophages promote a cytotoxic response mediated by classic inflammatory cytokines tumour necrosis factor- ⍺ (TNF-⍺), interleukin (IL) -1, IL-12, and IL-2351." (PMID 34732817, 2021). "Low-dose IFNβ treatment of tumor-bearing mice led to neutrophil polarization towards the anti-tumor N1 phenotype showing elevated Fas and TNFα expression and increased anti-tumor cytotoxicity." (PMID 34572138, 2021). "As an important part of the tumor microenvironment, macrophages secrete tumor necrosis factor-α (TNF-α) to promote the EMT of cancer cells." (PMID 34045431, 2021). "TNFα is also a proinflammatory cytokine playing a role in autoimmune disorders and neoplasm development." (PMID 33902677, 2021). "Recently, another scRNA-seq analysis indicated that the inflammatory-related pathways including IFNα and -γ signaling and TNF signaling were enriched in parental tumor tissue, whereas cell cycle related pathways were enriched in organoids." (PMID 33946033, 2021).
tumor (continued). "Locally restricted TNF induction occurs during an enforced cellular response to increasing osmotic pressure in the tumor microenvironment, for example." (PMID 33484626, 2021). "Meanwhile, the HFD-induced upregulation of serum tumor TNF-α and MCP-1 expression was also reduced by ART treatment." (PMID 33623531, 2021). "These lymphocytes can induce neoplastic regression through cell-cell interaction or by secreting several soluble molecules (such as IFN-γ and TNF) that inhibit tumor expansion." (PMID 33506055, 2021). "Consistently, the TNF-α serum level decreased significantly in the GL-pp group compared with that in the Tumor group or the T + SF group (p < 0.01)." (PMID 34305583, 2021). "Studies have shown that in the tumor microenvironment, the adhesion of tumor cells to stromal cells can promote stromal cells to secrete high levels of IL-6, tumor necrosis factor-α, and osteopontin as ligands of integrins to bind and activate integrins." (PMID 34295898, 2021). "Neutrophils are responsible for releasing several chemokines such as TNF-a and VEGF, which are implicated in angiogenesis, steroidogenesis, tumor growth, and metastasis, while, at the same time, interfering with normal T-cell response." (PMID 33918733, 2021). "In a MC38-OVA tumor model, GR-deficient CD8 T cells expressed higher IL-2, TNF-α, and IFN-γ; blocked tumor-growth and were less exhausted." (PMID 34691020, 2021). "Our results suggested that the microenvironment TNF-α activated hBMECs endothelial cells, induced adhesion molecules expression, and mediated the expression of adhesion molecule ligands on tumor cells." (PMID 34222020, 2021). "The CLC can also secrete several cytokines, such as IFN-γ and TNF-α, in order to block tumor growth and improve the prognosis of cancer patients." (PMID 34209764, 2021). "In general, it is well established that the chronic production of TNF-α in a tumor microenvironment contributes to malignant tumor progression by mediating tumor/stromal cell interactions, inducing a range of cytokines, and causing direct DNA damage." (PMID 33816268, 2021). "Shenling Baizhu powder increased the expression levels of IL-2, Interferon-γ (IFN-γ), and tumor necrosis factor-α (TNF-α) cytokines in the peripheral blood of tumor-bearing mice." (PMID 34803677, 2021). "In response to IFN-β signaling, neutrophils secrete pro-inflammatory cytokines TNF-α and nitric oxide (NO) to induce anti-tumor cytotoxicity." (PMID 34322780, 2021). "First, TNFα can decrease the recognition of tumor cells by melanocytic antigen-specific CD8+ T-cells and trigger the death of CD8+ T cells." (PMID 34604096, 2021). "TNF-α has been shown to have a dual role with opposite effects on tumor development: at low concentrations, TNF-α promotes angiogenesis and metastasis of tumor cells, and at high levels has antitumor effects." (PMID 34298820, 2021). "Human eosinophils were reported to exert TNF-α and granzyme A-mediated tumoricidal activity toward colon carcinoma cells, to induce tumor cell apoptosis and to promote cell-cell adhesion via IL-18 pathway." (PMID 34884995, 2021). "Initial reports showed the successful generation of immunocytokines containing lymphotoxin, TNF, granulocyte-macrophage colony-stimulating factor (GM-CSF), and IL-2 with direct and indirect anti-tumor capabilities in vitro." (PMID 33803078, 2021). "In the present study, we aim to investigate the role of miR-1224-5p and FOXO1 in dehydroepiandrosterone (DHEA)-induced mouse model of PCOS and TNF-α-treated human granulosa-like tumor (KGN) cells." (PMID 34637688, 2021). "Cytotoxic T cells specifically recognize the endogenous peptide MHC I complexes and kill tumor cells by expressing FasL or secreting TNF-α." (PMID 34604045, 2021). "This assortment empowers TNFα with a plethora of opposing roles in the processes of tumor cell survival (and apoptosis) and anti-tumor immune stimulation (and suppression), in addition to angiogenesis and metastases." (PMID 34445397, 2021).
tumor (continued). "Pro-inflammatory cytokines such as IL-1α, IL-1β, IL-6, TNF-α were constitutively expressed in tumor microenvironment to facilitate carcinogenesis." (PMID 34379689, 2021). "Overall, the combination of CD137, TNF, and IFNγ via intracellular detection was feasible and the use of CD137 improved the detection of tumor-specific reactive CD8+ TILs by more than 20% compared to the combination of TNF, IFNγ; and CD107a." (PMID 34707600, 2021). "Herein, we determined the effect of chronic DOX administration on serum levels of the inflammatory markers IL-6 and TNF-α, in juvenile tumor-free and tumor-bearing mice." (PMID 34445729, 2021). "This tumor microenvironment produces various factors such as interleukin-6 (IL-6), TNF, and TGF, all of which stimulate a transient EMT to promote cancer progression, invasion, and metastasis." (PMID 34064322, 2021). "We further found that miR155 over-expressing anti-CD19 CAR-T cells showed increased secretion of TNF-α, an inflammatory cytokine that exerts cytotoxic effects on a wide range of tumor cells, compared with RNAU6 anti-CD19 CAR-T cells." (PMID 35046962, 2021). "We also included interactions that described M2d phenotype, a tumor-associated-macrophage, and relevant inflammatory cytokines, such as TGF-β and TNF-α." (PMID 34177892, 2021). "TNF-α serves as a tumor promoter factor because it encourages cancer cell growth, proliferation, angiogenesis, and metastasis via the NFkB signaling pathway." (PMID 34833950, 2021). "In response to inflammation or tumor invasion, endothelial cells at the injury site will be stimulated by interleukin-1(IL-1), tumor necrosis factor-alpha (TNF-α), and other inflammatory factors, leading to the upregulation of E- and P-selectin expression." (PMID 34332597, 2021). "These pro-inflammatory factors, such as TNF-α and ROS, would stimulate tumor cells directly, affecting COX-2/PGE2 axis overexpression and activation." (PMID 34178680, 2021). "Caffeine, serving as an antagonist of the adenosine 2A receptor, has been shown to elevate levels of IFN-γ and TNF-α in tumor cells for the attenuation of cancer development rate." (PMID 34946538, 2021). "Yet, a few other studies proved penetration of TAMs along with TNF-α (cytotoxic M1 phenotype) in islets of tumours benefited in NSCLC and other malignancies." (PMID 34336101, 2021). "NK cells are rapid and potent responders in the anti-tumor immune response by producing cytotoxic granules, such as perforin and GzmB or inflammatory cytokines, such as IFN-γ and TNF to kill tumor cells directly." (PMID 34742349, 2021). "TNF thus has the potential to act as a double-edged sword with both pro- and anti-tumour action dependent on the surrounding environment and balance between activation and feedback inhibitory signals." (PMID 34944729, 2021). "The inflammatory cytokine TNF-α also stimulates tumor progression in non-small-cell lung cancer (NSCLC)." (PMID 34194957, 2021). "The rationale for exploring the TNF/IL12 combination, in addition to TNF alone, relies on the notion that IL12 can induce IFNγ in the tumor microenvironment, a cytokine known to be critical for the activity of vasculature-targeted TNF." (PMID 33952242, 2021). "M1 macrophages can inhibit tumor development by releasing tumor-suppressing molecules, including TNF-α." (PMID 34326840, 2021). "Salmonella can induce large amounts of blood flow into tumor tissues by increasing the secretion of TNF-α, which in turn leads to more Salmonella entering tumor tissues." (PMID 33717106, 2021). "As a key inflammatory mediator, TNF is able to induce tumour cell death and inhibit tumour proliferation." (PMID 34944729, 2021).
tumor (continued). "Mechanistically, mid- and high-dose RHWPs were found to collectively promote the anti-tumor immune response by increasing TNF-α, IFN-γ, and IL-2 secretion; T and B cell proliferation; and NK and macrophage effector functions." (PMID 33921554, 2021). "In endometrial cells, these two bacteria can also induce the production of IL-1α, IL-1β, IL-17α, and TNFα, pro-inflammatory cytokines which are involved in the carcinogenesis of various tumours." (PMID 34357126, 2021). "In fact, the upregulation and secretion of chemotactic cytokines (such as IFNγ and TNF-α) increase the recruitment of additional immune cells and alter the tumor microenvironment, stimulating the inhibition of immune exclusion of cancer signatures." (PMID 34638337, 2021). "The antibacterial and anti-tumor immune responses from the M1 macrophages are executed by releasing pro-inflammatory cytokines (such as IL-12, IL-1β, IL-2, IL-6, IL-23, and TNF-α), NO, ROS, and chemokines." (PMID 33883988, 2021). "Meanwhile, we showed that the serum TNF-α level increased in tumor-bearing mice subjected to SF; after the administration of GL-pp, the serum TNF-α level decreased." (PMID 34305583, 2021). "Considering the vital role of immune checkpoint molecules (PD-1, PD-L1, LAG3 and CTLA-4) in tumor immune microenvironment, we analyzed the expression of these molecules in two TNF patterns." (PMID 34691075, 2021). "Tumor cells produce inflammatory cytokines, such as tumor necrosis factor α and interleukin (IL)-1 and -6, and IL-6 is a major stimulator inducing CRP synthesis." (PMID 34548054, 2021). "This product, which resulted in DCs secreting IL2 and TNF-α, was found to be safe and also yielded a reduction in tumor size." (PMID 33996630, 2021). "Circulating tumor-derived PTHrP, MIP-1α, IL-1, IL-6, and TNF-α have been identified in the serum of ATL patients and are factors underlying the clinical tumor-associated bone manifestations." (PMID 34680215, 2021). "Despite TNFα’s denomination, in vitro reported tumor necrosis after high TNFα concentrations appeared a phenomenon that is not so straightforwardly translated to successful cancer treatments in vivo." (PMID 34445397, 2021). "Tumor necrosis factor alpha (TNFα) is a pleiotropic cytokine with both anti-tumorigenic and pro-tumorigenic activity, affecting tumor cell biology, the balance between cell survival and death." (PMID 33957885, 2021). "They serve as a primary source of EMT‐inducing signaling molecules, like IL6, TNFα and TGFβ, which promote a mesenchymal phenotype of tumor cells." (PMID 34459003, 2021). "To address these concerns, we measured the cytokines (such as TNF-α, IL-1β and IL-6) after we intravenously administered DMVs at 0.6 mg of DMVs which was the same dose used in the tumor therapy." (PMID 33537088, 2021). "DCs are recruited to infected tumors following S. Typhimurium administration, and those isolated from the tumor‐draining LNs produced more IL‐6, TNF‐α, and IL‐1β than DCs harvested from control mice." (PMID 34633664, 2021). "N1 produces high amounts of TNF-α and ROS, and has an increased phagocytic capacity, resulting in a decrease in tumor growth." (PMID 34283044, 2021). "CD8α ALN-1 improves the efficacy of ATCT and synergizes with neovasculature-targeted TNF for full tumor eradication." (PMID 34772757, 2021). "IL-1β and TNF-α have anti-tumor effects and can inhibit the growth and metastasis of tumors in vitro and in vivo." (PMID 34034714, 2021). "Both TNF-α and IFN-γ can cause tumour cell necrosis by destroying blood vessels and can also directly promote tumour cell apoptosis." (PMID 34565443, 2021). "As a rule, most proinflammatory cytokines including tumor necrosis factor α (TNF-α), interleukin 6 (IL-6) and interleukin 17 (IL-17), produced by either the host immune system or the tumor cells themselves, promote tumor progression." (PMID 34367064, 2021).